CLEC9A (C-type lectin domain containing 9A)
Diseases named in the same sentence as CLEC9A in open-access papers (continued):
Sharing a sentence is not in itself a finding about the gene and the disease.
cancer (continued). "Clinical trials are currently evaluating receptors that are highly expressed by DC subsets, such as DEC205, CLEC9A, and DEC205, for their potential in cancer immunotherapies, with promising results." (PMID 37371768, 2023). "Secreted gelsolin inhibits Clec9a-dependent cross presentation of antigen and dampens CD8+ T cell responses in a cancer model in mice." (PMID 35173718, 2022). "Human cDC1s express CD11clow, HLA-DR+, XCR1+, CLEC9A+, DNGR1, and CD141+ and play a key role in generating immunity against cancer." (PMID 35269652, 2022). "DC-targeting as a route to enhance the potency of cancer vaccines has been explored previously, with targeting of antigen to DC-specific markers such as XCR1, Clec9A and DEC205." (PMID 34944809, 2021). "To investigated the expression of CLEC9A and THBD, and assessed their correlations with overall survival in human cancers, we searched the TCGA database." (PMID 32655564, 2020). "Furthermore, Clec9A plays a crucial role in stimulating CD4+ T-cell responses, which are vital for facilitating CD8+ T-cell responses in cancer immunotherapies." (PMID 38250839, 2023). "We reanalyzed C-type lectin domain family 9 member A (CLEC9A) and CD141 (THBD) gene expression profiles from the Cancer Genome Atlas (TCGA) database and performed the Kaplan-Meier survival analysis of overall survival for several cancers according to their expression levels." (PMID 32655564, 2020). "Notably, loss of Clec9a completely reversed the relative resistance of sGSN-deficient mice to MCA-205 and B16F10 LA-OVA-mCherry tumors but did not impact growth of the same cancers in sGSN-sufficient hosts." (PMID 34081922, 2021).
infection (8 papers, 2016 to 2023). The state of being infected such as from the introduction of a foreign agent such as serum, vaccine, antigenic substance or organism. "By contrast, most mice (90%) immunised by targeting M2e to Clec9A survived the infection, although with substantial loss of body weight prior to recovery." (PMID 29263886, 2017). "All mice primed by targeting M2e to Clec9A survived the infection, with only a minimal transient body weight loss." (PMID 29263886, 2017). "Indeed, murine CLEC9A-deficient DCs are unable to facilitate cross-presentation of Vaccinia virus antigens upon infection." (PMID 29632536, 2018). "Purified cDC1s were transferred into Clec9A-DTR mice on day 6 post infection and lungs were harvested 4 days later." (PMID 30622538, 2018). "Compared to wild type mice, we observed significantly diminished numbers of virus-specific CD8+ T cells in Clec9A-DTR mice 5 weeks post infection." (PMID 30622538, 2018). "Of particular interest, IL-10 transcripts were strongly induced only in neonatal preCD8α Clec9A+ DCs after Lm actA-/- infection whereas adult preCD8α Clec9A+ DC and adult CD8α + DCs did not." (PMID 27074026, 2016). "Upon infection with Lm, we demonstrated that these preCD8α Clec9A+ DCs are endowed with regulatory properties that control the CD8+ T cell response through IL-10." (PMID 27074026, 2016). "We detected a 2-fold increase in Clec12a (p < 0.01), but a significant decrease in Clec7a (p < 0.001), Clec4b1 (p < 0.0001), and Clec9a (p < 0.001) at D9, further suggesting that Mincle was the preeminent CLR expressed in the lungs during infection." (PMID 34320039, 2021). "CLEC9A-mediated SYK activation specifically promotes the production of CXCL8 and IL-1β, which are central to neutrophil recruitment and activation during the early stage of infection." (PMID 29065139, 2017). "Upon infection with the highly immunogenic Herpes simplex virus, cytotoxic CD8 + T cell responses were reduced in mice lacking CLEC9A." (PMID 29632536, 2018). "Because reduced proliferation was detected at day 10 post infection, we speculated that the augmented numbers of activated LN CD8+ T cells in Clec9A-DTR mice from this time point may be related to a lack of egression from the LN." (PMID 30622538, 2018).
CLEC9A also shares sentences with these, for which no sentence is quoted: Arthritis (2 papers); allergic disease (1); allergic rhinitis (1); autoimmune disease (1); blood cancers (1); candidiasis (1); co-infection (1); colitis (1); colorectal carcinoma (1); fibrosarcoma (1); gastric cancer (1); head and neck squamous cell carcinoma (1); hematopoietic cancers (1); hepatocellular carcinoma (1); kidney (1); Listeria monocytogenes Infection (1); lupus (1); myositis (1); pancreatitis (1).